CRY2 (cryptochrome circadian regulator 2)
Diseases named in the same sentence as CRY2 in open-access papers (continued):
Sharing a sentence is not in itself a finding about the gene and the disease.
type 2 diabetes (15 papers, 2010 to 2026). "In conclusion our study has confirmed the association between type 2 diabetes and variants of the CRY2 gene and suggested a potential role for the CRY1 gene in disease development." (PMID 22485135, 2012). "In addition, we also found modest evidence for the association of CRY2-rs11605924 with combined IFG/type 2 diabetes." (PMID 21747906, 2011). "Since the association of CRY2-rs11605924 with combined IFG/type 2 diabetes was abolished after further adjustment for other confounding factors including family history of diabetes, lipid profile, medication information and hypertension, this result should be interpreted with caution." (PMID 21747906, 2011). "Recent research has revealed CRY2's involvement in regulating fasting blood glucose levels and its significant relevance to Type 2 diabetes." (PMID 40487778, 2025). "It has been demonstrated that the genetic variation of CRY2 is related to metabolic characteristics of type 2 diabetes." (PMID 29513728, 2018). "In contrast, type 2 diabetes was associated with rs12315175, close to the CRY1 gene, and rs2292912, located in the CRY2 gene, although statistical significance was nominal in both cases." (PMID 22485135, 2012). "In conclusion, our results confirmed the associations of GLIS3-rs7034200 with fasting glucose and risk of type 2 diabetes, and we also observed a moderate significant association between CRY2-rs11605924 and combined IFG/type 2 diabetes in Chinese Hans." (PMID 21747906, 2011). "The ROCAUC values of GLIS3-rs7034200 and CRY2-rs11605924 for the discrimination of type 2 diabetes were 0.543 and 0.511 respectively." (PMID 21747906, 2011). "SNPs from GIPR, TCF7L2, CRY2, GLIS3 and SLC30A8 were also associated with type 2 diabetes (p = 0.0487∼2.0×10−8)." (PMID 21103350, 2010). "Indeed, the risk of developing impaired fasting plasma glucose has been associated with polymorphisms in CRY2 while the polymorphism in ARNTL has been reported to increase the susceptibility to develop type 2 diabetes." (PMID 35267930, 2022). "Thus, ARNTL rs12363415 was connected with type 2 diabetes mellitus in women, while CRY2 rs2292912 and PER2 rs934945 were connected with dyslipidemia in men." (PMID 34066863, 2021). "Recent meta-analyses of GWA studies revealed fasting glucose-raising variants in CRY2 which, surprisingly, were not robustly associated with an increased risk for type-2 diabetes." (PMID 26726810, 2016). "Moreover, recent genome-wide association (GWA) studies revealed fasting glucose-raising variants in CRY2 which, surprisingly, were not robustly associated with type-2 diabetes." (PMID 26726810, 2016). "Impairment of the circadian clock genes such as CLOCK, BMAL1, cryptochrome (CRY1 and CRY2), and period (PER1, PER2, and PER3) contributes to the decrease in glucose tolerance, defective β-cell function, and the development of type 2 diabetes." (PMID 28352282, 2017). "We showed SNPs from seven loci, including GIPR, TCF7L2, MADD, CRY2, GLIS3, PROX1 and SLC30A8, had an effect on type 2 diabetes in our samples." (PMID 21103350, 2010). "Indeed, when mRNA expression levels were compared between cultured human islets from deceased donors, Per2, Per3, and Cry2 were under-expressed in type 2 diabetes mellitus (T2DM) patients compared to healthy donors, alluding that metabolic function correlates with robust clock rhythms." (PMID 31555652, 2019). "For CRY2-rs11605924 variant, we observed a moderate association with combined IFG/type 2 diabetes, but not with type 2 diabetes risk or its related traits." (PMID 21747906, 2011). "As to CRY2, we think however that CRY activation could be hazardous: our SNP data suggest that any supra-physiological enhancement of CRY2 signaling may favor liver fat accumulation and, thus, promote non-alcoholic fatty liver disease and type-2 diabetes." (PMID 26726810, 2016).
type 2 diabetes (continued). "Moreover, expression levels of per2 and cry2 were significantly lower in islets from human donors with type 2 diabetes and mRNA expression levels of per1 and per2 were significantly lower in the leucocytes of patients with type 2 diabetes than in non-diabetic controls." (PMID 24736612, 2014).
diabetes (13 papers, 2011 to 2025). "Similarly, a study performed in subjects from the United Kingdom and Pakistan reported that Cry1 and Cry2 polymorphisms rs2292912 and rs12315175, respectively, are associated with diabetes (P = 0.015 and 0.008, resp)." (PMID 27313610, 2016). "However, it is also necessary to say that the genetic component could be protecting our health such as in the case of polymorphisms associated with Per2 and Cry2 genes in diabetes, alcohol intake, and cancer." (PMID 27313610, 2016). "In the present study, B12 modulated several core clock genes (Bmal1, Cry1, Cry2, Per1, Per3), while other genes were primarily affected by diabetes (Bhlhe40, Hif3a, and Nr1d1)." (PMID 41463345, 2025). "Together with previous reports of associations between fasting glucose/diabetes and the MTNR1B and CRY2 loci, our data support a role for the circadian clock in the regulation of glucose homeostasis." (PMID 22485135, 2012). "A list of 15 known clock genes from the primary (Arntl, Clock, Npas2, Per1, Per2, Per3, Cry1, Cry2), secondary (Nrd1d1, Nr1d2, Rora, Rorb, Rorc), and accessory TTFL loops (Nfil3, Dbp) were selected to investigate the effect of diabetes on their rhythmic expression." (PMID 38039846, 2024).
mood disorder (11 papers, 2010 to 2023). A cognitive disorder a disturbance in which the person's mood is hypothesized to be the main underlying feature. "Associations between the gene Cry2 and winter depression, but also dysthymia and bipolar type I disorder support the view that the Cry2 gene has a role in mood disorders." (PMID 28468274, 2017). "Studies in humans have yielded evidence for an association of genetic variants of per2, per3 and cry2 with mood disorders such as SAD (seasonal affective disorder), bipolar disorder and dysthymia, respectively selective characteristics of these conditions." (PMID 26679264, 2016). "Moreover, it might be that CRY2 variants play a leading role in circadian hierarchy and thereby in the pathogenesis of mood disorders as well." (PMID 23951166, 2013). "Specifically, identified literature demonstrates that mood stabilizer valproic acid reduces CRY2 expression in the amygdala, suggesting the involvement of such clock genes in mood disorders and the potential to manipulate this pathway with CR mimetics." (PMID 38094940, 2023). "This new data, together with the earlier findings, reinforces the involvement of CRY2 in mood disorders." (PMID 23951166, 2013). "The finding is in line with a previous report on CRY2 in human mood disorder, thus strengthening the evidence for the contribution of circadian gene variations to mood disorders." (PMID 20856823, 2010). "Indeed, the observed rhythmic oscillation of Cry2 in the amygdala is disrupted in an animal model of a mood disorder characterized by increased anhedonic behavior following chronic mild stress." (PMID 25820768, 2015). "Hence, the present finding reinforces the significance of the previous reports implicating CRY2 in mood disorder in humans, and in rodent model." (PMID 20856823, 2010). "Phase control through the melatonin-guided interval of Per1/Per2 to Cry1/Cry2 expression peaks may have relevance to mood disorders, as the internal alignment and the melatonin signal (amplitude and phase) are abnormal in patients with bipolar disorder and those with winter depression in particular." (PMID 20195522, 2010).
bipolar disorder (10 papers, 2010 to 2024). A disorder of the brain that causes unusual shifts in mood, energy, activity levels and the ability to carry out day-to-day tasks. "Several core clock genes, such as PER1, PER3, CRY1, and CRY2, have been found to be associated with bipolar disorder." (PMID 39454958, 2024). "The A allele of rs10838524 (Cry2 SNP) was significantly overrepresented among bipolar disorder cases with rapid cycling compared to controls." (PMID 28468274, 2017). "In conclusion, this is the first report of genetic association between the circadian gene CRY2 and a severe form of human bipolar disorder." (PMID 20856823, 2010). "This study gives evidence that the CRY2 gene is associated with rapid cycling in bipolar disorder in Sweden." (PMID 20856823, 2010). "They observed that Cry2 is associated with rapid cycling in bipolar disorder patients." (PMID 28468274, 2017). "This is the first independent replication of the recent findings from gene expression analysis in white Americans that CRY2 is associated to bipolar disorder, and from haplotype frequency analysis in Swedes and Finns that CRY2 is associated to winter depression." (PMID 20856823, 2010). "CRY2 mRNA levels are lowered in blood mononuclear cells from depressed patients with bipolar disorder after total sleep deprivation in comparison to healthy controls, and CRY2 gene variation was associated with winter depression in both Swedish and Finnish patients." (PMID 20195522, 2010). "We tested the hypothesis that CRY2 gene variation is associated with bipolar disorder, and rapid cycling in particular, in a Swedish bipolar cohort." (PMID 20856823, 2010). "We propose that the circadian gene CRY2 is associated with rapid cycling in bipolar disorder." (PMID 20856823, 2010). "However, even though the CRY2 SNPs rs10838524 and rs3824872 in our study appeared not to be associated with bipolar disorder type 1, we cannot exclude the possibility of a true association for in particular the CRY2 SNPs rs7123390 and rs10838527 to bipolar disorder." (PMID 20856823, 2010). "In patients with depressive state of bipolar disorder, sleep deprivation induced significantly decreased Cry2 mRNA expression compared with healthy controls." (PMID 28468274, 2017). "As a novel finding we report here that CRY2 expression is reduced and non-responsive to sleep deprivation in depressed patients with bipolar disorder, suggesting that CRY2 plays a role in bipolar disorder." (PMID 20195522, 2010). "Abnormalities in CRY2 regulation would therefore leave the morning oscillator intact, which agrees with findings in patients with winter depression and those with bipolar disorder." (PMID 20195522, 2010). "Here, we assessed CRY2 gene expression in eight healthy volunteers for 48 hours and in 13 patients with bipolar disorder before and after a one-night sleep deprivation, and we report that CRY2 mRNA levels are reduced and unresponsive to sleep deprivation in depressed patients with bipolar disorder." (PMID 20195522, 2010). "There are reports that support a disturbed evening oscillator, in line with a possible CRY2 dysfunction, in bipolar disorder type 1 and winter depression, and there are data that indicate intact morning oscillator in patients with bipolar disorder and in winter depression patients." (PMID 20856823, 2010). "CRY2 mRNA expression levels were lowered in PBMCs from depressed patients with bipolar disorder." (PMID 20195522, 2010). "In addition, Cry2 mRNA levels were found to be lowered in blood mononuclear cells from depressed patients with bipolar disorder after total sleep deprivation in comparison to healthy controls, and Cry2 gene variation was associated with winter depression in both Swedish and Finnish patients." (PMID 28468274, 2017).
bipolar disorder (continued). "Four CRY2 SNPs spanning from intron 2 to downstream 3′UTR were analyzed for association to bipolar disorder type 1 (n = 497), bipolar disorder type 2 (n = 60) and bipolar disorder with the feature rapid cycling (n = 155) versus blood donors (n = 1044) in Sweden." (PMID 20856823, 2010). "In samples from patients in a depressive state of bipolar disorder (n = 13), sleep deprivation did not induce any increase in CRY2 mRNA levels." (PMID 20195522, 2010).
metabolic syndrome (9 papers, 2014 to 2024). A cluster of metabolic risk factors for CARDIOVASCULAR DISEASES and TYPE 2 DIABETES MELLITUS. "Other studies have shown associations between CRY1 and CRY2 polymorphisms and blood pressure in patients with metabolic syndrome, or associations between PER2 and BMAL1 polymorphisms and the non-dipper phenotype in 372 young hypertensive patients." (PMID 37298261, 2023). "It is observed that dyslipidemia is associated with rs2292912 CRY2 polymorphism in men, and patients carrying the CA or GA haplotypes of the CRY2 gene were 8.2 and 6.44 times likely to have dyslipidemia, respectively." (PMID 34066863, 2021). "This study’s haplotype analysis further supports this phenotype association of dyslipidemia with the CRY2 polymorphisms and haplotypes." (PMID 34066863, 2021). "Finally, the Cry2 SNP rs2292912 was a significant risk factor for the presence of dyslipidemia (OR 1.33, 95% CI 1.01–1.78; P = 0.049) and T2D (OR 1.48, 95% CI 1.08–2.05; P = 0.015)." (PMID 34141862, 2021). "Post-BWRP changes in the methylation levels of clock, cry2 and per2 genes occurred in the entire population, together with hypermethylation of clock and per3 genes in males and in subjects with metabolic syndrome." (PMID 36497566, 2022). "In contrast, rs2292912 in the CRY2 gene and rs934945 in the PER2 gene were associated with dyslipidemia in the men (p = 0.02, and <0.001, respectively)." (PMID 34066863, 2021). "Human research has recognized polymorphisms and transcription motifs of circadian rhythm genes, such as CRY2, CLOCK, ARNTL, PER2, or NPAS2, which are linked with hypertension, metabolic syndrome, or T2DM." (PMID 32050674, 2020). "Al-Sarraf and colleagues demonstrated that CRY2 is elevated in serum from patients with metabolic syndrome." (PMID 32722512, 2020). "Thus, metabolic syndrome, T2DM, and stroke are associated with CLOCK gene variants, while myocardial infarction is associated with CRY2 and PER2 gene variations." (PMID 32050674, 2020).
prostate carcinoma (9 papers, 2012 to 2025). A carcinoma that arises from epithelial cells of the prostate gland. "Eight of these, located in four genes, NPAS2 (2 SNPs), CSNK1E (3 SNPs), CRY1 (2 SNPs), and CRY2 (1 SNP), were significantly associated with prostate cancer risk." (PMID 30518396, 2018). "In particular, CRY1, CRY2, ROR, and BMAL1 have been implicated in the progression of prostate cancer." (PMID 39062777, 2024). "A reduction in the expression of circadian genes, including CLOCK, CRY1, CRY2, PER2, and BMAL1, has been associated with an increased risk of prostate cancer." (PMID 39062777, 2024). "Epidemiological studies of night shift workers provide strong evidence for the association between prostate cancer and gene variants, including BMAL1, NPAS2, CRY2 and PER2." (PMID 36291899, 2022).
leukemia (5 papers, 2021 to 2023). A malignant (clonal) hematologic disorder, involving hematopoietic stem cells and characterized by the presence of primitive or atypical myeloid or lymphoid cells in the bone marrow and the blood. "Although CRY1 and CRY2 were down-regulated in most of the identified results in leukemia patients, some cases showed a high expression of these genes." (PMID 35897788, 2022). "In medical research targeting clock genes, CRY1 may be related to the development of bladder cancer and leukemia, and therapeutic agents selective for CRY2 have been reported to be effective in treating glioblastoma, a malignant brain tumor." (PMID 37056311, 2023).
lung carcinoma (5 papers, 2018 to 2025). "Previous studies showed that circadian rhythm-related factors such as the ARNTL, CLOCK, RORA, RORB, CRY1, CRY2, and PER3 genes were associated with a higher risk of lung cancer." (PMID 36385012, 2022). "The log-rank test indicated a significant association of mRNA levels with overall survival (OS) of lung cancer patients (P < 0.05), and the TIMELESS, RORA, PER2, and CRY2 expressions were significantly correlated with progression-free survival (PFS) in lung cancer patients (P < 0.05)." (PMID 35078435, 2022). "Furthermore, we used the CCLE to analyze mRNA expression levels of PER1, PER2, PER3, CRY1, and CRY2 in lung cancer cell lines in current lung cancer research." (PMID 36385012, 2022). "Collectively, lung cancer patients with high expression of TIMELESS or low expression of RORA, PER1, PER2, or CRY2 had a significantly poorer prognosis in OS." (PMID 35078435, 2022).
neuroblastoma (5 papers, 2015 to 2024). Neuroblastoma (NB) is the most common solid, extracranial childhood tumor. "Our previous study has screened HMF-responding genes from neuroblastoma cells and verified that Cry2 was significant up-regulated after an 18 h short-term HMF exposure and down-regulated after a 48 h continuous HMF exposure." (PMID 27484904, 2016). "In human neuroblastoma cells, 2-day application of HMC upregulated about two hundred genes and downregulated ten times more genes, including CRY2 and MAPK1." (PMID 39337379, 2024). "In a recent transcriptome profiling analysis of human neuroblastoma cells, MAPK1 and CRY2 showed significant up- and down-regulation, respectively, during the first 6 h of a NZMF exposure." (PMID 26173003, 2015).
osteoporosis (5 papers, 2010 to 2025). A condition of reduced bone mass, with decreased cortical thickness and a decrease in the number and size of the trabeculae of cancellous bone (but normal chemical composition), resulting in increased fracture incidence. "Future studies will show whether specific pharmaceutical targeting of Cry2 or Per2 can serve as a new therapeutic avenue to treat bone loss conditions such as osteoporosis." (PMID 20634945, 2010). "Therefore, a distinct signaling, including STAT3/miR-7-5p/CRY2, has been revealed during osteoblast differentiation, which may provide a potential therapeutic strategy against disorders associated with osteoporosis." (PMID 31982773, 2020). "Our previous study has shown that the SNP rs2292910 of Cry2 is associated with osteoporosis in a Chinese geriatric cohort, because the SNP rs2292910 is located at the 3′ UTR region of CRY2, which may affect bone formation as a flanking sequence to be targeted by miR-7-5p." (PMID 31982773, 2020). "This study reveals that the circZNF367/FUS axis may accelerate osteoclasts differentiation by upregulating CRY2 in osteoporosis and suggests that targeting circZNF367 may have potential therapeutic effects on osteoporosis." (PMID 37434265, 2023). "Successful identification of miR-7-5p might provide an alternative therapeutic strategy against CRY2 to maintain the bone anabolism in the context of age-related bone disease, such as osteoporosis." (PMID 31982773, 2020). "In addition, our study firstly explored the relation among miR-27a-3p, CRY2 and ERK1/2, suggesting that miR-27a-3p/CRY2/ERK1/2 could play an important role in progression of osteoporosis." (PMID 33902432, 2021). "For instance, CircZNF367 has been shown to maintain CRY2 mRNA stability by interacting with FUS, thereby promoting osteoclast differentiation and osteoporosis." (PMID 40803272, 2025). "In conclusion, our study demonstrates that circZNF367 interacts with FUS to modulate the stability of CRY2 mRNA, thereby implicating the involvement of the circZNF367-FUS-CRY2 signaling pathway in osteoporosis." (PMID 37434265, 2023). "All of these results suggest that the relationship among CRY2, miR-7-5p, p-STAT3, and P300 likely exists in human MSCs, which may indicate a potential clinical application for a treatment strategy of osteoporosis." (PMID 31982773, 2020).